ORMDL3 (ORMDL sphingolipid biosynthesis regulator 3)
Diseases named in the same sentence as ORMDL3 in open-access papers (continued):
Sharing a sentence is not in itself a finding about the gene and the disease.
asthma (continued). "In rs11650680 of ORMDL3 gene the CT genotype is more prevalent in female asthma cases in comparison with female controls (OR = 1.99, 95% CI = 1.02–3.89, p = 0.03)." (PMID 29588858, 2018). "It is unclear if UPR signaling is abnormally regulated in asthma, although ORMDL3 has been shown to be increased in asthmatic bronchial epithelial cells, which leads to increased ATF6-mediated ER stress and UPR." (PMID 29472925, 2018). "Our findings take seemingly disparate risk factors and features of asthma, namely NO, HA (HAS2), ER stress (ORMDL3) and SMCs and demonstrate their interactions." (PMID 29966020, 2018). "ORMDL3 is an ER resident transmembrane protein that can be induced by allergens, IL-4/-13 via STAT6 activation and has been associated with asthma susceptibility." (PMID 29472925, 2018). "A critical asthma related protein, ORMDL3, has been reported to inhibit the activity of serine palmitoyl-transferase (SPT), the rate-limiting enzyme that catalyzes the first step of de novo biosynthesis of sphingolipids." (PMID 30345296, 2018). "Further testing on how smoking and other environmental factors regulate the effect of ORMDL3 SNPs on lung function is of interest, particularly in light of the uncertainty surrounding ORMDL3’s direct relation to asthma pathogenesis." (PMID 28740106, 2017). "To investigate the functional role of ORMDL3 during the development of asthma, we therefore developed a chronic Alternaria-induced AAD model." (PMID 27623174, 2017). "A recent study presumed that HRV-stimulated peripheral blood mononuclear cells increased the gene expression of ORMDL3 and of GSDMB which was associated with 17q21 variants and correlated with development of asthma." (PMID 28270165, 2017). "Specific to asthma, differential expression at the ZPBP2/GSDMB/ORMDL3 locus was identified resulting from allele-specific chromatin remodeling mediated by CTCF." (PMID 29228930, 2017). "Our data reinforce the findings of asthma GWAS, placing ORMDL3 as an important mediator in the development of allergen-induced AHR." (PMID 27623174, 2017). "Some genes detected by GWAS have shown the potential as asthma biomarkers in a specific age group, e.g. ORMDL3/GSDMB in children." (PMID 27658857, 2016). "For ORMDL3, a potential role in asthma by influencing endoplasmatic reticulum stress reaction, oxidative stress reaction, calcium homeostasis, and phospholipid metabolism has been shown." (PMID 27510897, 2016). "The contribution of other known atopy variants, such as those in the DENND1B gene, located on chromosome 1q31 and the ORMDL3 gene, located on chromosome 17q12 to the asthma phenotype is also possible." (PMID 27990118, 2016). "Three asthma-risk SNPs (rs4065275, rs8076131 and rs12603332) overlapped DHS in the first intron of ORMDL3; this ∼3.0 kb intronic region was also highly enriched for the H3K27ac mark, suggestive of active enhancer activity, in CD4+ T cells but not monocytes." (PMID 27848966, 2016). "Recent work has unveiled the relevance of ORMDL3 in inflammation; however, most findings were confined to airway inflammation, remodeling and hypersensitivity in the context of asthma." (PMID 26603569, 2015). "This large study identified genes on chromosomes 2 (IL1RL1/IL18R1), 6 (HLA-DQ), 9 (IL33), 15 (SMAD3), 17 (ORMDL3/GSDMB), and 22 (IL2RB) associated with asthma." (PMID 26557257, 2015). "Another potential mechanism linking ORMDL3 to asthma is through alterations in sphingolipid homeostasis and de novo sphingolipid synthesis." (PMID 26637347, 2015). "Polymorphisms in ADAM33, ORMDL3/GSDMB and IL4 were associated with childhood asthma in a group of children with recurrent wheeze." (PMID 25768087, 2015). "Although the region covering the ORMDL3, GSDMA and GSDMB genes is the most replicated one, the keratin (KRT) cluster has also been shown to be associated with asthma in a previous GWAS study." (PMID 26672748, 2015).
asthma (continued). "Polymorphisms in ADAM33 (rs511898 and rs528557) and ORMDL3/GSDMB (rs7216389) were negatively associated and polymorphisms in IL4 (rs2070874 and rs2243250) were positively associated with childhood asthma." (PMID 25768087, 2015). "The extended chromosome 17 locus has also been implicated previously as containing SNPs associated with asthma spanning three main genes; ZPBP2/GSDMB/ORMDL3 and it is still unclear which genes/polymorphisms underlie these associations." (PMID 24066901, 2013). "Increased transcript level of ORMDL3 had been found in Epstein-Barr-virus-transformed lymphoblastoid cell lines from children with asthma and in human rhinovirus stimulated peripheral-blood mononuclear cells." (PMID 24204796, 2013). "Further extensive studies are needed to answer the question of what 13-cis RA target molecule initiates the inhibitory effect on ORMDL3 expression since it is of potential beneficial action on asthma." (PMID 24204796, 2013). "The combination of specific genetic variants in ORMDL3 and RORA increased the risk for current asthma, with ORs of 2.1 (CI 1.2-3.6) and 3.2 (CI 2.0-5.0) among the BAMSE and PARSIFAL children, respectively." (PMID 24260339, 2013). "Although this study focused exclusively on the potential role of ORMDL3 in asthma pathogenesis, it is possible that neighboring genes such as GSDML contribute to disease susceptibility at this locus." (PMID 23369242, 2013). "Genome-wide association (GWA) studies on asthma have suggested that several polymorphisms in several genes, including ORMDL3-GSDMB, DENND1B, HLA-DP, SLC30A8, IL1RL1-IL18R1, IL33, SMAD3, TSLP, and NOTCH4 are associated with asthma." (PMID 23861779, 2013). "STAC2 is within a locus with 16 other genes including ORMDL3, which has been suggested to be the most likely causal gene based previous genetic and functional studies in IBD and asthma." (PMID 24068945, 2013). "In conclusion, the asthma-associated HapA haplotype variants of the ZPBP2 promoter region and the putative promoter for the minor ORMDL3 isoform had higher in vitro promoter activity compared to the variants associated with the HapB haplotype." (PMID 22271045, 2012). "Recently, the first GWAS for asthma identified ORMDL3 as a new asthma candidate gene, and subsequent studies confirmed the association of polymorphisms in the chromosome region with asthma in different ethnic groups." (PMID 21985515, 2011). "Joint analysis of disease GWAS and eGWAS identified potential candidate genes for asthma (ORMDL3), Crohn's disease (PTGER4), NIDDM (PHACS), thalassemia (HBS1L). eGWAS is a useful approach to detect disease SNPs with a functional role." (PMID 21569597, 2011). "The present study aimed to analyze and compare the distribution pattern of the ORMDL3 gene among children with and without asthma in order to evaluate its association with childhood asthma susceptibility." (PMID 41939571, 2026). "This may explain why rs7216389, rather than rs4065275, was associated with exacerbations in this study, suggesting a greater involvement of GSDMB than ORMDL3 in exacerbations in type 2–low asthma." (PMID 40687950, 2025). "It remains uncertain whether GSDMB or ORMDL3 plays a critical role in exacerbations in patients with type 2–low asthma, although the role of GSDMB has received more attention recently." (PMID 40687950, 2025). "As we did not see an association with the causal asthma SNP rs2304580 or at least one of the SNPs in GSDMB or ORMDL3, it suggests that the genetic risk at this locus for both asthma and for RSV infection (severity and viral load) are different." (PMID 40867500, 2025). "Additionally, recent studies have shown a potential gene-gene interaction between ORMDL3 and GSDMB, with co-expression of both genes linked to increased asthma susceptibility." (PMID 39906448, 2025). "Taken together, these findings suggest that type 2 inflammation may not be essential for the relationship between rs7216389 in GSDMB/ORMDL3 and asthma exacerbations." (PMID 40687950, 2025).
asthma (continued). "Furthermore, ORMDL3, which is highly expressed in asthma, exacerbates airway inflammation and remodelling by activating the JNK1/2–MMP-9 pathway, representing a potential novel therapeutic target for asthma treatment." (PMID 40986971, 2025). "The rs6967330 variant in cadherin-related family member 3 (CDHR3), which encodes a receptor for human rhinovirus C, was also analyzed, because studies on CDHR3 in adults are limited, despite its identification as a risk factor for asthma exacerbation in children similarly to GSDMB/ORMDL3." (PMID 40687950, 2025). "Research on ORMDL3 has primarily focused on its relationship with asthma and rhinovirus infections." (PMID 40126553, 2025). "Motivated by the well-known asthma-related gene ORMDL3, we decided to investigate if the pollen season’s methylation effects could affect AR and contribute to the development of asthma." (PMID 38699230, 2024). "Interestingly, previous studies suggest potential roles for GSDMB and ORMDL3 expression in asthma pathobiology." (PMID 39299705, 2024). "Additionally, it has been demonstrated in the past that mice that express higher amounts of human GSDMB or human ORMDL3 have an asthma phenotype 17." (PMID 40104184, 2024). "The ORMDL3 and GSDMB genes are strongly associated with asthma." (PMID 38629073, 2024). "Moreover, an association with both asthma and Crohn’s disease was found for gene loci DENND1B, SMAD3 and SLC22A4/5 (5q31/IBD5), while the ORMDL3 gene variants present in Crohn’s disease and ulcerative colitis were also associated with childhood-onset asthma." (PMID 37835065, 2023). "In addition, SETDB1 interacts with the asthma-related gene SETDB2; the latter antagonizes the KDM4C gene to control H3K9 methylation, which affects the expression of ORMDL3, a well-known asthma-related gene." (PMID 37569643, 2023). "Furthermore, the expression of ORMDL3 in eosinophils seems to play a role in recruitment, attachment and activation of eosinophils in asthma." (PMID 36206293, 2022). "ORMDL3 may contribute to asthma progression by modulating store-operated calcium entry and lymphocyte activation, eosinophil trafficking and activation, and sphingolipid homeostasis." (PMID 36078171, 2022). "In addition to being highly correlated with asthma, ORMDL3 is also involved in many important signal transduction processes such as regulating cell growth, differentiation, senescence, and programmed cell death, thus playing an important role in many diseases." (PMID 35972600, 2022). "In addition, the ORMDL3 gene is located at the 17q21 region and plays an important role in asthma pathogenesis." (PMID 36078171, 2022). "Characterized more than 317,000 SNPs in DNA from 994 patients with childhood onset asthma and 1,243 non-asthmatics, using family and case-referent panels, confirmed that Genetic variants regulating ORMDL3 expression contribute to the risk of childhood asthma." (PMID 35295917, 2022). "Though the genetic regulation of sphingolipid homeostasis is complex, and the mechanisms linking ORMDL3 to asthma are incompletely understood, there is mounting evidence that shifts in sphingolipid hemostasis have an important role in childhood asthma and early-life wheeze." (PMID 34931265, 2021). "We assessed methylation at two asthma-associated genes, IL13 and ORMDL3, in blood samples collected from children with and without asthma and fractionated white blood cell types from healthy adult controls." (PMID 33971943, 2021). "In terms of immune and inflammatory cells expressing ORMDL3, CD4+ cells expressing SNPs linked to ORMDL3 have enhanced Th2 responses, suggesting that ORMDL3-regulated pathways in CD4+ cells may be the key cell implicating ORMDL3 in asthma." (PMID 33661765, 2021). "ORM1-like 3 (ORMDL3) has strong genetic linkage to childhood onset asthma." (PMID 33661765, 2021). "Previous studies reported that GSDMB and ORMDL3 are associated with asthma, but their association with HF was not reported." (PMID 35126453, 2021).
asthma (continued). "In support of this, ORMDL3 has been shown to be upregulated in asthma." (PMID 34288557, 2021). "As ASM hyperplasia is a feature of asthma, we investigated whether increased expression of ORMDL3 in ASM influenced proliferation utilizing a BrdU assay." (PMID 33661765, 2021). "While many studies in mice use tracheal smooth muscle, an advantage of this study is that we used mouse bronchial smooth muscle (of greater relevance to asthma than tracheal smooth muscle), which expressed copy numbers of human ORMDL3 similar to that noted in ASM in human patients with asthma." (PMID 33661765, 2021). "GSDMB and ORMDL3 were also confirmed to be shared between asthma and HF using TWAS in our study." (PMID 35126453, 2021). "Animal models have connected ORMDL3 and sphingolipids to clinical features of asthma." (PMID 34931265, 2021). "Genome wide association studies (GWAS) initially identified a link between alleles within the 17q21 asthma-susceptibility locus, childhood asthma, and overexpression of the ORMDL sphingolipid biosynthesis regulator 3 (ORMDL3), an inhibitor of de novo sphingolipid synthesis." (PMID 34931265, 2021). "In this brief review, we focus on growing evidence suggesting that heightened ORMDL3 expression specifically in CD4+ T lymphocytes, the central orchestrators of adaptive immunity, constitutes a major underlying mechanism of asthma pathogenesis by skewing their differentiation and function." (PMID 33424845, 2020). "Defining the mechanisms by which altered ORMDL3 expression perturbs CD4+ T cell differentiation and function should illuminate new treatment paradigms for patients with 17q12–21 risk SNPs, and expand of our current understanding of asthma pathogenesis." (PMID 33424845, 2020). "Various functions assigned to ORMDL3 may impact asthma pathogenesis by altering the physiology of several cell types." (PMID 33424845, 2020). "As ORMDL3 is a major regulator of SPT, the rate limiting enzyme that catalyzes all sphingolipid biosynthesis, we posit that increased ORMDL3 expression and dysregulation of sphingolipid levels likely exacerbates asthma through effects in multiple cell types, including T cells." (PMID 33424845, 2020). "Moreover, a transcriptomic study of ORMDL Sphingolipid Biosynthesis Regulator 3 (ORMDL3) found that a variant in that gene might influence the route of anti-inflammatory action of glucocorticoids by modifying the transcriptional activation of ORMDL3 in subjects with asthma." (PMID 31992292, 2020). "In this review, we explore how intrinsic ORMDL3 overexpression in human T cells may contribute to asthma pathogenesis." (PMID 33424845, 2020). "For example, strong evidence is found for site-specific DNAm as an intermediary via which disease variants regulate ORMDL3, GSDMB, and JAZF1 expression by CD4+ T cells in RA, MS, and asthma, and a similar mechanism in relation to ANKRD55 and IL6ST is limited to RA and MS." (PMID 31945409, 2020). "This genomic region consists of a number of genes, including ORMDL3, GSDMB, IKZF3, ZPBP2, and GSDMA that are in LD and may either be individually or jointly responsible for the asthma association." (PMID 30541564, 2018). "The reduced activity of SERCA by ORMDL3 may contribute to airway remodeling in asthma as Ca2+ homeostasis in airway smooth muscles is important for airway remodeling, regulating cell proliferation, cell spreading, and pro-inflammatory cytokine release." (PMID 29472925, 2018). "Another example is that ORMDL3/17q locus is associated with asthma in multiple studies in the European ancestry but not in African ancestry asthmatic individuals." (PMID 29855310, 2018). "Because of its additional chaperone function it would be of interest to determine whether this drug also has efficacy in patients with asthma carrying genetic variations in the ORMDL3 locus." (PMID 27623174, 2017).
asthma (continued). "Overall, our results suggest that physiological alteration in the levels of ORMDL3 and GSMDB induced by the asthma-risk allele may be sufficient to modulate the functional capacity of T cells." (PMID 27848966, 2016). "Allergens induce ORMDL3 expression in airway epithelium leading to increased expression of asthma-associated chemokines, metalloproteases and the unfolded protein response (UPR), which may implicate the potential link between ORMDL3 and asthma." (PMID 27658857, 2016). "In addition to the ORMDL3 intronic enhancer, two other DHS regions that overlap asthma-risk SNPs were also present in 25–60% of the cell types analysed, that is were not strictly cell-type specific." (PMID 27848966, 2016). "An association with asthma was only seen in non-farming offspring for hypermethylated cord blood ORMDL3 and STAT6." (PMID 26052354, 2015). "While the functions of ORMDL3 are incompletely understood, it is known to be involved in sphingolipid metabolism and de novo sphingolipid synthesis, suggesting altered sphingolipid metabolism as a contributing factor in asthma." (PMID 26637347, 2015). "Irrespective of the exposure or disease status, methylation of several asthma and allergy-related genes changed over time (IL-4, IL-13, ORMDL3, RAD50), indicating their involvement in developmental processes, while Treg-related genes (FOXP3, RUNX3) remained unchanged." (PMID 26052354, 2015). "In allergic eosinophilic disorders such as asthma, ORMDL3 could also mediate eosinophil trafficking, recruitment and degranulation via integrin and CD4850." (PMID 26603569, 2015). "Many groups consider ORMDL3 as an ‘asthma gene’; however, it should be acknowledged that the identified SNPs associating this gene to asthma susceptibility are not located in the gene itself." (PMID 23369242, 2013). "Anyhow, the facilitation of ATRA on ORMDL3 production should be taken in to account since this may become another side effect of Vitamin A application on asthma treatment." (PMID 24204796, 2013). "Elucidating the molecular mechanism that control transcription of ORMDL3 gene may yield insights into the mechanism how misregulation of ORMDL3 leads to the pathology of asthma." (PMID 23577138, 2013). "This study implicated a locus near ORMDL3 – a gene not previously suspected to have a role in asthma susceptibility." (PMID 23028483, 2012). "The asthma-associated region 17q12-q21 harbors three genes, the zona pellucida binding protein 2 (ZPBP2), gasdermin B (GSDMB) and ORM1-like 3 (ORMDL3), that show allele-specific differences in expression levels in lymphoblastoid cell lines (LCLs) and CD4+ T cells." (PMID 22271045, 2012). "Recently, the first genome-wide association study (GWAS) of asthma in European subjects identified a novel region containing the ORM1-like 3 (ORMDL3) gene at chromosome 17q21 strongly associated with childhood asthma and ORMDL3 transcript abundance." (PMID 21985515, 2011). "Review of previous T1D genome-wide association results revealed that four (human leucocyte antigen (HLA), gasdermin B/ORM1 (Saccharomyces cerevisiae)-like/gasdermin B/, GSDMB/ORMDL3/GSDMA and IL2RB) of ten loci recently reported to be associated with asthma were associated with T1D (p≤0.005)." (PMID 22069270, 2011). "The first GWAS for childhood asthma identified ORMDL3 (and GSDMB) also present in the 17q21 region." (PMID 22188591, 2011). "And these SNPs may also influence asthma onset by regulating the expression of ORMDL3." (PMID 40110046, 2025). "Consequently, it is essential to explore whether histone acetylation mediated via p30 has a key role in the overexpression of ORMDL3 in asthma." (PMID 41008562, 2025). "Consequently, targeting the overexpression of ORMDL3 and uncovering the mechanisms that regulate its activity may offer promising avenues for developing new asthma therapies." (PMID 41008562, 2025).